LRFN5 (leucine rich repeat and fibronectin type III domain containing 5)
Description:
Cell adhesion molecule that mediates homophilic cell-cell adhesion in a Ca(2+)-independent manner. Promotes neurite outgrowth in hippocampal neurons.
Synonyms: C14orf146; SALM5; FIGLER8
Tractability: Antibody: UniProt predicts a signal peptide or a membrane-spanning region. PROTAC: its protein half-life has been measured.
Gene: Protein-coding gene on chromosome 14 (41,606,733 to 41,904,549, forward strand). Ensembl gene ENSG00000165379.
Subcellular location: Membrane
Gene Ontology:
Molecular function: protein binding
Biological process: negative regulation of inflammatory response; negative regulation of macrophage activation; regulation of presynapse assembly; synaptic membrane adhesion
Cellular component: cell surface; GABA-ergic synapse; glutamatergic synapse; postsynaptic density membrane; membrane
Genetic constraint (gnomAD): Loss-of-function variants: 18 observed, 42.45 expected, observed/expected ratio (o/e) 0.42, 90% interval 0.29 to 0.63. The upper end of that interval is the gene's LOEUF score, 0.63, which puts it in group 2 of 6, group 1 being the genes least tolerant of losing a copy. Missense variants: 751 observed, 885.67 expected, observed/expected ratio (o/e) 0.85, 90% interval 0.8 to 0.9. Synonymous variants: 329 observed, 323.19 expected, observed/expected ratio (o/e) 1.02, 90% interval 0.93 to 1.12.
Homologues: Orthologues: macaque LRFN5 (99% identical), chimpanzee LRFN5 (97% identical), pig LRFN5 (97% identical), mouse Lrfn5 (97% identical), rabbit LRFN5 (97% identical), rat Lrfn5 (96% identical), guinea pig LRFN5 (96% identical), tropical clawed frog lrfn5 (82% identical), zebrafish lrfn5a (73% identical). Paralogues in human: LRFN2 (50% identical), LRFN1 (49% identical), LRFN3 (43% identical), LRFN4 (42% identical), SLIT3 (22% identical), SLIT2 (22% identical), SLIT1 (21% identical), LRRN1 (20% identical), LRRN2 (19% identical), LINGO1 (18% identical), LRRN3 (18% identical), LINGO2 (17% identical), and 13 more.
Diseases named in the same sentence as LRFN5 in open-access papers:
LRFN5 is named in the same sentence as 15 diseases in open-access papers, as found by Europe PMC text mining. Sharing a sentence is not in itself a finding about the gene and the disease. The quoted sentences say what the papers report.
autism (7 papers, 2015 to 2023). Persistent deficits in social interaction and communication and interaction as well as a markedly restricted repertoire of activity and interest as well as repetitive patterns of behavior. "Hub genes of the turquoise module included one GABA receptor encoding genes such as Gabrb1, one glutamate receptor gene (Grid2) and genes tightly associated with synaptic development and autism (Nrxn1, Lrfn5, Plcb1, Erc2, Frmpd4, Tanc2, Ctnnd2, Dmd)." (PMID 34021132, 2021). "This puts MDGA2 in line with other neuronal cell adhesion molecules of the immunoglobulin family, such as contactins, NRCAM, CADM1 and LRFN5 that are implicated in axon migration and guidance and were associated with autism." (PMID 25572423, 2015).
depression (5 papers, 2017 to 2025). "Recent genome-wide association studies on major depressive disorder (MDD) have implicated LRFN5 and OLFM4, but their expressions and roles in MDD are still completely unclear." (PMID 37280213, 2023). "Lrfn5 mediates cell adhesion for synaptic plasticity and coincides with AD and major depressive disorder." (PMID 40979532, 2025). "However, till now, very little is known about the expression and function of LRFN5 and OLFM4 in patients with depression." (PMID 37280213, 2023). "Interestingly, we also found correlations between the levels of these aberrant clinical biochemical indices and the levels of LRFN5 or OLFM4, which further supported their involvement in depression." (PMID 37280213, 2023). "However, in cases where depression is a downstream consequence of chronic pain, its onset may be influenced by lifestyle and other ‘above-the-skin’ factors that also operate downstream of chronic pain, rather than as a more direct result of synaptic changes related to LRFN5 expression levels." (PMID 31748543, 2019).
autism spectrum disorder (1 paper, 2016). A spectrum of developmental disorders that includes autism, and Asperger syndrome. "SALM5/Lrfn5, a SALM/Lrfn family adhesion molecule implicated in autism spectrum disorders (ASDs) and schizophrenia, induces presynaptic differentiation in contacting axons, but its presynaptic ligand remains unknown." (PMID 27225731, 2016).
chronic pancreatitis (1 paper, 2024). A chronic inflammatory process causing damage and fibrosis of the pancreatic parenchyma. "Furthermore, the investigators found that LRFN5 and PXDN did not exhibit significant methylation frequency in patients with chronic pancreatitis (CP) compared to healthy individuals, providing better distinction than the panel of ADAMTS1 and BNC1 alone." (PMID 38672671, 2024).
parasite infections (1 paper, 2024). "A copy number variation was also identified in the LRFN5 gene in indigenous Nguni cattle, which are resistant to diseases and parasite infections." (PMID 39795948, 2024).
cancer (3 papers, 2022 to 2024). A tumor composed of atypical neoplastic, often pleomorphic cells that invade other tissues. "Gpr125+ cells at the distal tips of pubertal ducts express particularly high levels of genes, such as Sox 11, Aldh1a3, and Lrfn5, associated with stemness, neurite outgrowth, and cancer, respectively." (PMID 35302059, 2022). "For example, MAD2L2 and LRRC61 are risk factors in most cancers, while PFKFB3, ESAM, SYNM, and LRFN5 act as protective factors in most cancers." (PMID 38124743, 2023). "We further integrated our methylation results with RNA-seq data, and we identified 11 genes, including six related to immune functions (AHR, LRFN5, NTRK2, RSPO2, SAMSN1, and TFEC), and three related to cancer (SLC12A5, SORCS1, and TP63)." (PMID 39795948, 2024).
tumor (3 papers, 2022 to 2023). "Therefore, these target genes can also provide new directions for future tumor treatment, especially the five genes DLC1, LRFN5, NOVA1, POU3F2 and PRICKLE2 which were positively related to the overall survival time." (PMID 35578189, 2022). "Sixteen nearby genes showed higher expression in non-cancerous tissues, including seven with almost no expression in tumor (HCN1, SLC22A2, FAM3D, LRFN5, LINC01612, LINC02512, and CNBD1)." (PMID 37509325, 2023).
LRFN5 also shares sentences with these, for which no sentence is quoted: developmental delay (2 papers); Insulin resistance (1); Intellectual disability (1); intraductal papillary mucinous neoplasms (1); microcephaly (1); pancreatic cancer (1); psychiatric disorder (1); schizophrenia (1).